DISC1 (DISC1 scaffold protein)
Diseases named in the same sentence as DISC1 in open-access papers (continued):
Sharing a sentence is not in itself a finding about the gene and the disease.
schizophrenia (continued). "DISC1 has been implicated in major mental illness by rare mutations that have been linked to neuropsychiatric disease, including schizophrenia, bipolar disorder, and autism spectrum disorder." (PMID 30410030, 2018). "This action can counteract DISC1 deficiencies observed in neural progenitor cells derived from induced pluripotent stem cells from schizophrenia patients with a DISC1 frameshift mutation." (PMID 28727686, 2018). "First, to the best of our knowledge, mutations with large risk to schizophrenia have been reported in at least five genes, DISC1, NRXN1, PRODH, SHANK3, and SLC1A1 according to records in OMIM." (PMID 30745909, 2018). "Disrupted-in-Schizophrenia-1 (DISC1) is a susceptibility gene for schizophrenia based on genetic linkage and association studies." (PMID 29610762, 2018). "Considering that disrupted in schizophrenia 1 (DISC1) interruption had been implicated in mental illness, Srikanth and his colleges employed the 3D model to investigate the role of DISC1 in psychiatric disease." (PMID 30534474, 2018). "Mutations in high-risk gene candidates for schizophrenia such as neuregulin 1, DISC1, and dysbindin have all been demonstrated to disturb NMDA receptor regulation." (PMID 29449801, 2018). "In conclusion, and despite the limitations, these findings provide further genetic evidence to support the impact of both DISC1-interacting proteins and genes whose expression is modulated by genetic variants in the DISC1 pathway on schizophrenia." (PMID 28630456, 2018). "The DISC1 gene was identified from patients with familial mental disorders and has been considered a critical susceptibility gene for schizophrenia." (PMID 30459650, 2018). "This important caveat also applies not only to the DISC1 Regulome gene set, in which 16 genes were nominally associated at the gene level with schizophrenia, but likely to the majority of brain-expressed gene sets." (PMID 28630456, 2018). "Another mutation is a 4 bp deletion at the end of DISC1 exon 12, which was identified in a proband with schizophrenia in an American pedigree." (PMID 30410030, 2018). "DISC1, known for identification via rare structural variant in schizophrenia, has also been associated with ASDs." (PMID 28076348, 2017). "Deficits in neurite outgrowth, possibly involving dysregulation of risk genes neuregulin-1 (NRG1) and disrupted in schizophrenia 1 (DISC1) have been implicated in psychiatric disorders including schizophrenia." (PMID 28198409, 2017). "The team found that overexpression of DISC1 affected the expression of the fruit fly counterpart to human ‘neurexin,’ a known risk factor for conditions including schizophrenia and autism spectrum disorders." (PMID 29079805, 2017). "Disrupted-in-schizophrenia-1 (DISC1) is a risk gene associated with major mental illnesses, including schizophrenia and depression." (PMID 29029423, 2017). "DISC1 was first associated with a variety of brain disorders, including schizophrenia, mood disorders, and autism." (PMID 29029423, 2017). "Genetic association studies have identified a single nucleotide polymorphism (SNP) in DISC-1 gene, which increases the risk of developing schizophrenia." (PMID 28933765, 2017). "Humans that carry a mutation in DISC1 present with a variety of psychiatric conditions, including depression, schizophrenia and bipolar disorder." (PMID 28334933, 2017). "The SCZ risk gene, disrupted in schizophrenia 1 (DISC1), has been associated with neuropsychiatric conditions." (PMID 29156684, 2017). "DISC1 is implicated in neurogenesis and mutations in DISC1 have been shown to produce a schizophrenia-like phenotype in both mice and humans." (PMID 29197324, 2017). "In a DISC1 mutated mouse model of schizophrenia, NAP treatment was shown to ameliorate behavior improving cognition and reducing anxiety." (PMID 28933765, 2017).
schizophrenia (continued). "FEZ1 has been associated with the dendritic growth of neurons and risk of schizophrenia via its interaction with DISC1 (disrupted in schizophrenia 1)." (PMID 28928414, 2017). "We also identify evidence for differential DNA methylation associated with the increased polygenic burden for schizophrenia, including in the vicinity of DISC1, a gene previously implicated in the disease by a highly penetrant balanced translocation." (PMID 28011714, 2017). "The disrupted-in-schizophrenia 1 (DISC1) gene was identified as a genetic risk factor for chronic mental illnesses (CMI) such as schizophrenia, bipolar disorder and severe recurrent depression." (PMID 28275106, 2017). "DISC-1 is another gene involved in cytoskeletal remodeling and its alteration is associated to schizophrenia." (PMID 28933765, 2017). "Numerous studies have suggested a genetic predisposition to schizophrenia, and many genes, including DISC1, catechol-O-methyltransferase (COMT), neuregulin 1 (NRG1), and DTNBP1, have been identified as candidate susceptibility genes." (PMID 28937620, 2017). "The disrupted in schizophrenia 1 (DISC1) protein is a promising candidate susceptibility factor for major mental illness." (PMID 26553875, 2016). "The expression of the DISC1-Boymaw fusion protein results from the schizophrenia-associated chromosomal translocation, which interrupts DISC1 in a Scottish pedigree." (PMID 26553875, 2016). "The gene disrupted in schizophrenia 1 (DISC1) has been associated with increased risk for neuropsychiatric conditions." (PMID 26756905, 2016). "SR interacts with DISC1 in astrocytes and pathogenic disruption of SR-DISC1 binding leads to depletion of D-serine levels and schizophrenia-like behavior in mice." (PMID 26941605, 2016). "We have shown that the schizophrenia-associated DISC1-Boymaw fusion protein, which targets to mitochondria, localizes to mitochondria in MAP2 positive dendritic processes." (PMID 26553875, 2016). "In schizophrenia, the DISC1 gene has been considered an important risk factor and in iPSC-derived DISC1 mutant neurons, pre-synaptic vesicle release was impaired." (PMID 26903887, 2016). "Collectively, our data support a mechanism whereby impaired DISC1 function leads to aberrant mitochondrial dynamics and dendritic morphogenesis, a causative factor in schizophrenia and other major mental illness." (PMID 26553875, 2016). "Disrupted-in-Schizophrenia-1 (DISC1) gene has been linked to schizophrenia and related major mental illness." (PMID 27244370, 2016). "DISC1 network of PPIs involved CDC5L indicates the protein or complexes that have been linked to schizophrenia." (PMID 28117656, 2016). "We also demonstrate that the schizophrenia-associated DISC1-Boymaw fusion protein acts in a dominant negative fashion to disrupt mitochondrial trafficking and fusion, as well as decreasing the area of ER-mitochondria contacts." (PMID 26553875, 2016). "Here we demonstrate that the schizophrenia-associated protein, DISC1, interacts with Miro1 and Miro2 as well as TRAK1 and TRAK2 to affect axonal and dendritic transport of mitochondria." (PMID 26553875, 2016). "Previous studies have shown that candidate genetic susceptibility factors for schizophrenia, DISC1 and dysbindin-1, function both pre- and postsynaptically through interaction with partners to regulate neurotransmitter release and signal transduction." (PMID 28036092, 2016). "The DISC1 protein is implicated in major mental illnesses including schizophrenia, depression, bipolar disorder, and autism." (PMID 26553875, 2016). "Multiple genetic studies have shown an association between DISC1 and schizophrenia, bipolar disorder, major depression, and autism." (PMID 26553875, 2016). "DISC1 is a prominent schizophrenia risk gene, which was originally identified at the breakpoint of a balanced chromosomal translocation cosegregating with mental disorders in a large Scottish kindred." (PMID 27725886, 2016).
schizophrenia (continued). "The Disc1 is one of the risk genes for psychiatric disorders such as schizophrenia and mood disorders." (PMID 26074774, 2015). "The DISC1-Boymaw fusion protein (arising from a schizophrenia-associated chromosomal translocation, which interrupts DISC1 in a Scottish pedigree) was shown to localize to the mitochondria, disrupts mitochondrial dynamics and affects dendritic development." (PMID 26729171, 2015). "Two other Disc1 mutant mouse lines with point mutations at Q31L and L100P, which show schizophrenia and depression related phenotypes, respectively, were also subjected to MIA." (PMID 26074774, 2015). "Neuregulin-1 and DISC1 signalling pathways have both been linked to neurodevelopment and schizophrenia." (PMID 26656849, 2015). "Here, we set up to evaluate NAP, as a treatment against cognitive deficits and impairments in Foxp2 expression in a DISC1 mutated mouse model for schizophrenia." (PMID 26553741, 2015). "Those Disc1 mice allow to directly examine the impact of a depression- and schizophrenia-related risk gene mutation on behaviour and the activity of neuronal networks involved in the control of cognitive functions." (PMID 25735038, 2015). "Further, our study demonstrates the feasibility of utilizing Disc1 genetic manipulations in rats, providing an alternate animal model to elucidate the functional role of schizophrenia risk genes in adult neurogenesis and hippocampal function." (PMID 26161071, 2015). "In particular, the DISC1 Cys allele was positively associated with schizophrenia in a study of Han Chinese subjects." (PMID 24146131, 2015). "The genetic studies in the NFBC 1966 have focused especially on DISC1 (disrupted-in-schizophrenia 1), finding associations between DISC1 and social anhedonia." (PMID 26090224, 2015). "Mutated disrupted in schizophrenia 1 (DISC1), a microtubule regulating protein, leads to schizophrenia and other psychiatric illnesses." (PMID 26553741, 2015). "Adult neurogenesis has also been implicated in a familial form of schizophrenia where there is a disrupted-in-schizophrenia (DISC1) mutation, leading to abnormal maturation of adult-born GCs." (PMID 26347618, 2015). "Previously, acute Disc1 knockdown in the adult mouse dentate gyrus induced a loss of proliferating cells and generated both schizophrenia-related and depression-related phenotypes." (PMID 25272038, 2014). "Overall, our +/del model based on a naturally occurring mutation of DISC1, represents a mouse model that encompasses several phenotypes related to schizophrenia and other mental illnesses diagnosed in the Scottish family." (PMID 25126062, 2014). "Among the many proposed susceptibility genes for schizophrenia, Disrupted in schizophrenia-1 (DISC1) is currently one of the best supported candidates." (PMID 25126062, 2014). "ATF4 is also decreased in the frontal cortex of schizophrenia patients and its binding to DISC1 (disrupted-in-schizophrenia 1) is compromised by schizophrenia-associated DISC1 mutations." (PMID 25071442, 2014). "The present study using behavioral genetic approaches provides an insight into the role of Disc1 L100P and other single nucleotide variants in behavioral phenotypes associated with psychiatric disorders such as schizophrenia." (PMID 25487992, 2014). "Disrupted in schizophrenia 1 (DISC1) is a risk factor for a spectrum of neuropsychiatric illnesses including schizophrenia, bipolar disorder, and major depressive disorder." (PMID 25272038, 2014). "DISC1 is a promising candidate gene for susceptibility to schizophrenia, and is involved in newborn neuron migration in the SGZ." (PMID 24676388, 2014). "Group I PAKs are activated by RAC-PAK signaling to promote axon connectivity, and synapse formation, in the developing brain in a pathway regulated by another schizophrenia risk gene DISC1 [MIM:60521]." (PMID 24474471, 2014).
schizophrenia (continued). "Mouse models for the genetic mutation of Disc1 are of relevance for unraveling the impact of gene disruption on neural integrity associated with schizophrenia." (PMID 25487992, 2014). "We demonstrate that PAK7 is co-expressed with DISC1 in developing brain and further investigation of the role of the mutation in synaptic mechanisms salient to schizophrenia is warranted." (PMID 24474471, 2014). "Disrupted-in-schizophrenia 1 (DISC1) is a promising candidate susceptibility gene for psychiatric disorders, including schizophrenia, bipolar disorder and major depression." (PMID 25487992, 2014). "And finally, VENs express high levels of disrupted in schizophrenia SZ-1 (DISC1), which is implicated in neuronal migration during development, and are typically disrupted in schizophrenia." (PMID 24672457, 2014). "Disrupted-in-Schizophrenia1 (DISC1) is one of the most frequently discussed susceptibility loci for schizophrenia." (PMID 25506321, 2014). "Disrupted-In-Schizophrenia 1 (DISC1) is a candidate risk factor for schizophrenia, bipolar disorder and severe recurrent depression." (PMID 24092329, 2014). "Several studies on mutant mice of DISC1, one of the susceptible genes for schizophrenia, showed the reduction of parvalbumin-expressing interneurons in prefrontal cortices and CA region of hippocampus." (PMID 24528488, 2014). "Through expression data and polymorphisms, FEZ1 has been related to the etiology of schizophrenia and also interacts with the DISC1 protein - one of the most studied genes in this disease." (PMID 24116125, 2013). "Genetic manipulation of schizophrenia susceptibility genes in rodents, such as DISC1, NRG1/ErbB4, and COMT has been largely explored as well." (PMID 24027504, 2013). "For example, a long ncRNA disrupted in schizophrenia 2 (DISC2) is a NAT overlapping the DISC1 gene and has been implicated in schizophrenia, bipolar disorder and autism." (PMID 24007600, 2013). "A recent study revealed that signals from ErbB2:ErbB3 complexes in the neocortex regulate the expression of disrupted schizophrenia 1 (DISC1), which has been implicated in the genetics of schizophrenia." (PMID 23408472, 2013). "Among these, FEZ1 was recently shown to interact with DISC1, a susceptibility gene for schizophrenia and other mental disorders." (PMID 24063311, 2013). "This short distance migration can be largely extended under pathological conditions such as knockdown of the schizophrenia susceptibility gene Disc1 or seizures, where newborn neurons can migrate even beyond the boundaries of the granule cell layer." (PMID 23667508, 2013). "DISC1 is one of the most studied genes associated with schizophrenia, and mutations in the gene are generally associated with decreased function of the protein." (PMID 23882188, 2013). "An additional gene whose disruption predisposes to schizophrenia was first identified in 2000 in a large Scottish family, and named Disrupted-In-Schizophrenia 1 (DISC1)." (PMID 23618463, 2013). "The gene DISC-1 (disrupted-in-schizophrenia-1), in which mutations have been associated with schizophrenia and other serious mental illnesses in a large pedigree, is expressed in CD11b+ microglia, as well as in neurons." (PMID 23690824, 2013). "One such gene is disrupted-in-schizophrenia 1 (DISC1) which was originally identified as a potential susceptibility gene for schizophrenia and related psychiatric disorders in a large Scottish pedigree." (PMID 23346419, 2012). "We show that expression of the DISC1 c-terminal truncation variant that is associated with Schizophrenia alters the frequency of mEPSCs and the kinetics of evoked glutamate release." (PMID 22479520, 2012). "Disrupted in Schizophrenia 1 (DISC1) is one of the most promising candidate genes for schizophrenia with abundant supporting evidence from linkage, association, gene expression studies and animal models." (PMID 22363459, 2012).
schizophrenia (continued). "In this context, the dynactin complex has been reported to interact with dysbindin and disrupted-in-schizophrenia-1 (DISC1), both of them being confirmed as risk genes of schizophrenia." (PMID 22441714, 2012). "DISC1 was identified to be associated with schizophrenia; although it had well characterized protein domains such as coiled-coil domains, leucine-zipper domains, and nuclear localization and export signals, nothing was inferred about its function." (PMID 23209562, 2012). "Overall, our results support a direct presynaptic function for the schizophrenia-associated gene, DISC1." (PMID 22479520, 2012). "The spectrin-like repeat region of Kalirin has also been shown to interact with DISC1, a genetic risk factor for schizophrenia which plays an important role in activity-dependent spine elongation by promoting Kalirin-7/Rac-1 interactions." (PMID 22548195, 2012). "DISC1 was identified as a schizophrenia susceptibility gene because a chromosomal translocation that results in a c-terminal truncation of the DISC1 gene was found to co-segregate with major mental illness in an extended Scottish pedigree." (PMID 22479520, 2012). "Disrupted-in-Schizophrenia 1 (DISC1) is considered to be a candidate susceptibility gene for psychiatric disorders, including schizophrenia, bipolar disorder, and major depression." (PMID 22348257, 2012). "The pathophysiology of schizophrenia is believed to involve defects in synaptic transmission, and the function of many schizophrenia-associated genes, including DISC1, have been linked to synaptic function at glutamatergic synapses." (PMID 22479520, 2012). "PDE4A5 expression has been identified in primary cortical neurons, and PDE4A5 has been shown to bind with disrupted in schizophrenia 1 (DISC1), a risk factor for schizophrenia, bipolar disorder, and major depression." (PMID 23028463, 2012). "Up to now, researches have demonstrated that DISC1 is a susceptibility gene for mental disorders such as autism, schizophrenia and bipolar disorder." (PMID 21569632, 2011). "Genetic studies had indicated that DISC1 was a susceptibility gene for schizophrenia, depression, bipolar disorder and schizoaffective disorder." (PMID 21569632, 2011). "As one of the most interesting candidate genes for major mental illness, DISC1 have been demonstrated to associate with schizophrenia, depression, bipolar disorder and schizoaffective disorder in several independent populations by multiple association studies." (PMID 21569632, 2011). "DISC1 is a key “hub gene” in schizophrenia linked, via its interactome, to many other schizophrenia susceptibility gene products." (PMID 22567321, 2011). "One example of this is the widely studied schizophrenia susceptibility gene DISC1 that was first identified as a balanced translocation in a large Scottish family." (PMID 23074677, 2011). "Its association with the MT-associated factors Lis1 and DISC-1 (the lissencephaly and schizophrenia-causing proteins, respectively), has incriminated it as a potential candidate in developmental and neuropsychiatric disorders." (PMID 21283621, 2011). "Mutations in the DISC1 gene are strongly associated with major psychiatric syndromes such as schizophrenia." (PMID 20531939, 2010). "DISC1 has been reproducibly linked to psychiatric disorders involving impairment of cognitive function, particularly schizophrenia." (PMID 20531939, 2010). "Associations have been found between mutant DISC1 genes and neurocognitive deficit symptoms specific for schizophrenia and bipolar disorders." (PMID 19128481, 2009). "The human TRAX gene is adjacent to DISC1, a gene implicated in schizophrenia, and haplotypes covering both DISC1 and TRAX in humans have been reported to be associated with schizophrenia." (PMID 19370154, 2009). "A SzGene database search listed 24 schizophrenia-association studies for DISC1 from 2001 to February 2008." (PMID 19128481, 2009).